IL10 (interleukin 10)
Diseases named in the same sentence as IL10 in open-access papers (continued):
Sharing a sentence is not in itself a finding about the gene and the disease.
inflammatory bowel disease (continued). "Strategies relying on the local delivery of IL‐10 in situ have been explored for some bacteria, such as L. lactis or Bifidobacterium bifidum in inflammatory bowel disease, with some promising preliminary results in clinical trials." (PMID 36598022, 2023). "Furthermore, enhanced or unresolved intestinal barrier damage underlies disease pathology in inflammatory bowel disease (IBD), including loss of IL-10 and increased tissue neutrophil accumulation." (PMID 36538527, 2023). "There is evidence of IL-10 and IL-10R deficiencies which are monogenic inborn errors of immunity (IEI) causing early-onset inflammatory bowel diseases (IBD)." (PMID 37359549, 2023). "In inflammatory bowel disease, the anti-inflammatory cytokine IL-10 is pivotal for controlling the inflammatory responses to enteric organisms." (PMID 36832826, 2023). "Since the spontaneous development of chronic intestinal inflammation in mice deficient in interleukin-10 (IL-10−/−) was described more than two decades ago, this experimental model is one of the major approximations in the study of inflammatory bowel disease (IBD) pathophysiology." (PMID 36699599, 2022). "In this context, the significance of BEV-elicited IL-10 from BMDM is implied from its role in the prevention of inflammatory bowel disease." (PMID 36439842, 2022). "Inflammatory conditions, such as inflammatory bowel disease, have focused on IL-10 as a treatment but are yet to see clinical improvements due to challenges with drug stability, bioavailability, and the complexity of immune responses." (PMID 36158966, 2022). "Clinically, IL-10 has also been found to be associated with immune-mediated inflammatory diseases such as inflammatory bowel disease, systemic lupus erythematosus or rheumatoid arthritis, expounding the important immunomodulatory function of IL-10." (PMID 36524108, 2022). "Recently, Il-10 mRNA delivered by exosomes has been reported for the treatment of inflammatory bowel disease." (PMID 36559192, 2022). "To date, the therapeutic administration of recombinant human IL-10 has been studied in clinical trials for different diseases such as rheumatoid arthritis, inflammatory bowel disease, and psoriasis." (PMID 36148228, 2022). "Researchers observed that probiotics can mitigate inflammatory bowel disease through the regulation of IL-10." (PMID 34712822, 2021). "DPT cells are also present in the intestinal epithelial layer in inflammatory bowel disease, and can inhibit Th1-induced intestinal inflammation in an IL-10-dependent manner." (PMID 34095321, 2021). "Defects in interleukin 10 (IL10) and its receptors are particularly involved in very early onset inflammatory bowel disease (VEOIBD)." (PMID 33849446, 2021). "These probiotics were ranked based on the IL-10/IL-12 cytokine ratio, indicating their ability to attenuate inflammatory bowel disease in vivo." (PMID 33572768, 2021). "Further research should be pursued to evaluate B. bifidum BGN4 [pBESIL10] producing IL-10 as a treatment for various inflammation-related diseases, including inflammatory bowel disease, rheumatoid arthritis, allergic asthma, and cancer immunotherapy." (PMID 33468130, 2021). "In models of autoimmunity including inflammatory bowel disease or nephritis, IL-10 effects largely depend on the inhibition of IL-17A pathways." (PMID 34772416, 2021). "Another study utilizing modified mRNA LNPs investigated therapeutic delivery of interleukin 10 (IL-10) into Ly6C+ inflammatory leukocytes in a mouse model of inflammatory bowel disease (IBD)." (PMID 34683969, 2021). "Because inflammatory bowel disease develops in IL-10 knockout mice, IL-10 is thought to have an inhibitory effect on inflammation." (PMID 34064515, 2021). "It earned its recognition following the functional secretion of the heterologously expressed cytokine interleukin-10, which alleviated the symptoms of the inflammatory bowel disease (IBD) in the IBD model mouse in vivo." (PMID 32024292, 2020).
inflammatory bowel disease (continued). "Treg-produced IL-10 promotes tolerance in the intestinal mucosa and defects in IL-10 signaling trigger inflammatory bowel disease in mouse and human." (PMID 33584708, 2020). "IL10 knockout mice develop colitis, comparable to human inflammatory bowel disease and are hypersensitive to inflammatory stimuli." (PMID 32240179, 2020). "HCK was previously found to be genetically associated with inflammatory bowel disease and predicted as a causal factor that regulates NOD2, IL10 and ALOX5." (PMID 32565911, 2020). "IL‐10−/− mice are a model for human inflammatory bowel disease and develop inflammation in the distal ileum and proximal colon." (PMID 32350866, 2020). "Deficiencies or mutations in IL10 or the IL10 receptor (IL10R) are found to cause early onset of inflammatory bowel disease (IBD) in humans." (PMID 32240179, 2020). "The aberrant expression of IL10 and FOXP1 was associated with various immune‐mediated inflammatory diseases, including RA, SLE and inflammatory bowel disease, and the importance of IL‐10 in immune regulation for AIH has been recognized." (PMID 32808463, 2020). "The importance of IL-10 in intestinal immunity is also illustrated by the identification of mutations in IL-10, IL-10RA, and IL-10RB genes in children suffering from inflammatory bowel disease (IBD)." (PMID 30915067, 2019). "Genome-wide association studies and experimental animal models showed an essential role of the IL-10 in inflammatory bowel disease." (PMID 31849652, 2019). "The down-regulated IL-6 and IL-6/IL-10 ratio confirmed the anti-inflammatory effect of salidroside for enteritis and other inflammatory bowel diseases." (PMID 30944705, 2019). "Early-onset (within the first months of life) of severe inflammatory bowel disease (EO-IBD), i.e., Crohn's disease and ulcerative colitis (UC), can be caused by IL-10 and IL10- receptor deficiencies." (PMID 31849949, 2019). "Furthermore, mutations in the IL-10 receptor are associated with inflammatory bowel disease (IBD) in human, while IL-10 knockout mice readily develop IBD." (PMID 31148944, 2019). "The anti-inflammatory cytokine IL-10 is of interest because it has been investigated as a potential therapeutic to reduce acute inflammation in inflammatory bowel disease." (PMID 30890187, 2019). "For example, AHR activation is protective in inflammatory bowel disease, partly due to increased IL10 expression." (PMID 30184180, 2018). "The anti-inflammatory effects of garlic extracts result from its dual direct effect on IL-10 and IL-12 in inflammatory bowel disease." (PMID 30008785, 2018). "That cluster, induced by the activation of AhR in inflammatory bowel disease, was able to promote an inflammatory response by inducing the Th17 response and suppressing IL-10 production." (PMID 30648118, 2018). "For example, IL10 expression can be induced using AHR agonists as a protective mechanism in inflammatory bowel disease, or repressed by an endogenous VDR agonist (calcitriol) during pregnancy to enhance responses to microbial infections." (PMID 30184180, 2018). "Among them, a L. lactis-based interleukin-10 (IL-10) formulation has been subjected to phase II clinical trials of inflammatory bowel disease (IBD) therapy." (PMID 28321412, 2017). "Accordingly, defects of IL10, IL10RA, or IL10RB genes cause very early-onset inflammatory bowel disease (IBD) including infantile-onset IBD (IOIBD)." (PMID 26822028, 2016). "We observe approximately 20 hours separation when comparing the two earliest pathways (lysosome and inflammatory bowel disease) with the two slowest pathways (IL-22BP and IL-10) selected from the 8 most accurate pathways." (PMID 27532264, 2016). "The finding indicated that endogenous IL-10 is important to inhibit the inflammatory response, while IL-10 has a dual role in the inflammatory bowel disease." (PMID 26751073, 2016).
inflammatory bowel disease (continued). "The anti-inflammatory effect of the garlic extract by IL-10 deregulation and the reduction of IL-12 production in Inflammatory bowel disease (IBD) prevents IL-12 from binding to its receptor on T and NK cells, causing inhibition of the production of IFN-γ." (PMID 25961060, 2015). "IL-10 plays a crucial role in tissue homeostasis, by preventing bystander tissue damage during inflammatory processes such as inflammatory bowel disease." (PMID 25071732, 2014). "This is not dissimilar to the gut where bacteria colonized, but not germ free mice, with IL-10 deficiency develop severe enterocolitis, and humans with defects in IL-10 signaling pathway develop early onset inflammatory bowel disease." (PMID 24734032, 2014). "Moreover, IL-10 polymorphisms and rarer mutations in the IL-10 and IL-10R genes have been associated with inflammatory bowel diseases (IBD) and severe enterocolitis in infants, respectively." (PMID 25014110, 2014). "Some of these studies indicate that treatment with B cells producing IL-10 can modulate the course of arthritis, inflammatory bowel disease and EAE." (PMID 23738007, 2013). "Future work will utilize these plasmids to test the effects of IL-4 and IL-10 in other chronic murine inflammatory bowel disease models." (PMID 24314293, 2013). "These IL-10−/− mice under normal conditions show increased inflammatory responses and develop inflammatory bowel disease." (PMID 22681958, 2012). "It was indeed recently demonstrated that anti-TNF antibodies induce IL-10 producing macrophages in an Fc-dependent manner and that these immunoregulatory macrophages are involved in mucosal healing in inflammatory bowel disease." (PMID 22563430, 2012). "Unfortunately, several clinical attempts to treat inflammatory bowel disease using IL-10 have failed probably due to low mucosal availability and proinflammatory effects of high-dose systemic IL-10 administration." (PMID 21811497, 2012). "The anti-inflammatory effects, combined with direct induction of IL-10, are of interest with respect to possible treatment of inflammatory bowel diseases as well as in support of a healthy immune system." (PMID 20331905, 2010). "Administration of recombinant IL-10 (rIL-10) reduces disease severity in experimental models of diabetes, rheumatoid arthritis, and inflammatory bowel disease." (PMID 19771172, 2009). "Thus, we sought to elucidate the therapeutic effect of targeting delivery of Grem1 and IL-10 in SETD2-deficient and DSS-induced inflammatory bowel disease." (PMID 39990215, 2025). "Furthermore, exosomes from human umbilical cord mesenchymal stem cells reduced the severity of inflammatory bowel disease in mice by increasing IL-10 levels and decreasing TNF-α, IL-1β, and IL-6 in the colon tissues." (PMID 40822681, 2025). "For example, targeting DC-SIGN to enhance IL-10 production could be a strategy to treat chronic inflammatory conditions in animals, such as inflammatory bowel disease or autoimmune skin disorders." (PMID 40076949, 2025). "In line with this, the beneficial effects of the ethanolic extract of T. polium in an animal model of acute inflammation, and extract of T. persicum in animal model of inflammatory bowel disease were accompanied by high expression of IL-10 and low expression of TNF-α and IL-1β." (PMID 39452128, 2024). "Tregs can secrete interleukin-10 (IL-10) to regulate the responses of Th17 lymphocytes and Th1 lymphocytes, and suppress the production of pro-inflammatory interleukin-17 (IL-17) by intestinal immune cells to prevent inflammatory bowel diseases." (PMID 40217405, 2024). "The systemic administration of IL‐10 in humans for the treatment of different pathologies (including inflammatory bowel disease, allergic asthma, and solid tumours) has been tested in different clinical trials but failed in the clinical outcome of these patients due to various problems." (PMID 36598022, 2023).
inflammatory bowel disease (continued). "In addition, EPS which were isolated from L. plantarum YW11 reduced the production of the proinflammatory cytokines (TNFα, IL-1β, IL-6, IFN-γ, IL-12 and IL-18) and up-regulated IL-10, and this resulted in an amelioration of inflammatory bowel disease symptoms." (PMID 36769176, 2023). "Thus, IL-10−/− mice are the most common animal model used to elucidate the pathogenesis of human gastrointestinal diseases such as inflammatory bowel diseases (IBDs)." (PMID 37373511, 2023). "ToxoROP16I/III promotes the polarization of M2 cells, and enhances the synthesis of Arg-1, IL-10, transforming growth factor-β1, and IL-13, which may ameliorate the pathogenesis of inflammatory bowel disease in an in vitro experimental model." (PMID 35911679, 2022). "Thus, Il-10 mRNA-loaded exosomes have been used for the treatment of inflammation related diseases, including atherosclerosis and inflammatory bowel disease." (PMID 36559192, 2022). "Furthermore, the treatment of IL‐10 KO mice with 1,25D3 resulted in the suppression of inflammatory bowel disease (IBD) symptoms." (PMID 33559391, 2021). "Furthermore, genetic variants in interleukin-10 (IL-10), IL-10 receptor(IL-10R), X-linked inhibitor of apoptosis protein (XIAP), and forkhead box P3 (FOXP3) have been linked to very early-onset inflammatory bowel disease (VEOIBD)." (PMID 34956195, 2021). "Similarly, there was a distinct sex differences on microbiota in the control group which also disappeared in the IL-10 KO-induced inflammatory bowel disease model." (PMID 34249773, 2021). "Further in vivo and clinical research should be pursued to evaluate therapeutic properties of B. bifidum BGN4 [pBESIL10] synthesizing IL-10 as a treatment for various inflammation-related diseases, including inflammatory bowel disease, rheumatoid arthritis, allergic asthma, and cancer immunotherapy." (PMID 33468130, 2021). "These pleiotropic effects may explain the failures in clinical trials of direct IL‐10 administration in inflammatory bowel disease, and there is therefore an argument for a targeted IL‐10 approach to control for any aberrant pro‐inflammatory effects." (PMID 34320225, 2021). "Interleukin 10 - is it a therapeutic option in inflammatory bowel disease?" (PMID 33691712, 2021). "From in vivo studies, osthole (50 mg/kg) could benefit inflammatory bowel disease by increasing IL-10 and reducing the levels of TNF-α and IL-17." (PMID 32028721, 2020). "Furthermore, IL-33 treatment promotes IL-10 production by B-cells in adult mice, thus protecting these mice from induction of inflammatory bowel disease." (PMID 32751234, 2020). "IL-10 is known to have antiinflammatory effects in inflammatory bowel diseases." (PMID 31999939, 2020). "A similar study showed that human umbilical cord MSC-EVs reduced TNF-α, IL-1β, IL-6, iNOS, and IL-7 genes while increasing the expression of IL-10 gene in the colon tissues relieving inflammatory bowel disease’s symptoms in mice with dextran sulfate sodium induced colitis." (PMID 33613514, 2020). "IL-10 polymorphisms were considered to be connected with multiple disease susceptibility such as ischemic stroke, pulmonary tuberculosis, HIV-1, nasopharyngeal carcinoma and multiple sclerosis, gastric cancer and inflammatory bowel disease." (PMID 31822303, 2019). "Our previous studies found that Bcl2L12 was involved in immune deregulation by interfering with the expression of IL-10 in peripheral B cells of patients with allergic rhinitis 16 or inflammatory bowel disease 32 and facilitating the development of Th2 polarization." (PMID 31410196, 2019).
inflammatory bowel disease (continued). "A previous study has shown that IL-10−/− mice that develop a form of inflammatory bowel disease (a model for Crohn’s disease) gained more weight and developed lower pathological scores, lower TNF-α concentrations, and lower SAA content when mice were fed a TGFβ-2-containing diet." (PMID 29675026, 2018). "This study opens new avenues in cell specific delivery of mRNA molecules and ultimately might introduce IL-10 mRNA as a novel therapeutic modality to inflammatory bowel diseases." (PMID 30374059, 2018). "These activities are mediated, at least in part, by the production of IL10 and may control a variety of autoinflammatory diseases including inflammatory arthritis, inflammatory bowel disease, autoimmune diabetes, SLE, and SS." (PMID 28326325, 2017). "IL-10 has also been shown to play a role in chronic gastrointestinal problems, and its modulation by probiotic bacteria has been observed in patients with ulcerative colitis and inflammatory bowel disease." (PMID 28758133, 2017). "It will be important to test this further in experimental settings such as inflammatory bowel disease, where impaired expression of IL-10 may have profound consequences." (PMID 28265004, 2017). "Although deleterious mutations in interleukin-10 and its receptor molecules cause severe infantile-onset inflammatory bowel disease, there are no reports of mutations affecting this signaling pathway in Japanese patients." (PMID 26822028, 2016). "In an IL-10 KO inflammatory bowel disease mouse model, it has been demonstrated that wild-type (WT) BM transplantation can ameliorate the severity of inflammation in the intestine, suggesting that BM-secreted IL-10 plays an anti-inflammatory role." (PMID 27314021, 2016). "Recently, the mechanism of B cells inhibitory capacity has focused on their ability to produce IL-10, and have convincingly demonstrated that B cells producing IL-10 can limit disease in animal models of experimental autoimmune encephalomyelitis, inflammatory bowel disease, and rheumatoid arthritis." (PMID 23189166, 2012). "IL-10 is critical in the gut, as mice with a Treg-specific deficiency in IL-10 develop inflammatory bowel disease, but not systemic autoimmunity." (PMID 22912633, 2012). "Polymorphisms in the IL10 gene region have been reported to be associated with ulcerative colitis (UC), type I diabetes, and severe juvenile rheumatoid arthritis, and mutations in the genes encoding the subunits of the IL-10R were found in patients with inflammatory bowel disease (IBD)." (PMID 22969768, 2012). "Recent studies have shown that IL-10 producing B-cell subsets with varying phenotypes can regulate different immune responses in numerous mouse models, such as inflammatory bowel disease (IBD), EAE, type 1 diabetes, collagen-induced arthritis, contact hypersensitivity and during parasitic infection." (PMID 20625435, 2010). "Inflammatory bowel disease (IBD) stands out as the most extensively studied condition in terms of IL‐10 therapy." (PMID 41573378, 2026). "Zwicker and Xu reported that IL-34 might inhibit TNF-α expression in macrophages 1 and overlap with the anti-inflammatory cytokine IL-10-secreting macrophages in inflammatory bowel disease and infectious disease models, suggesting the anti-inflammatory potential of IL-34." (PMID 39883639, 2025). "Furthermore, peptidoglycan and muropeptides derived from Lactobacillus salivarius are key substances for alleviating inflammatory bowel disease and have been shown to induce IL-10-producing dendritic cells that upregulate the immunosuppressive pathway of indoleamine 2,3-dioxygenase." (PMID 40016142, 2025). "Early efforts concentrated on intestinal disorders such as inflammatory bowel disease (IBD), where genetically modified Lactococcus lactis was engineered to produce the anti-inflammatory cytokine interleukin-10 (IL-10) in the gut." (PMID 41007667, 2025).